MMP3 (matrix metallopeptidase 3)
Diseases named in the same sentence as MMP3 in open-access papers (continued):
Sharing a sentence is not in itself a finding about the gene and the disease.
periodontitis (continued). "Our data from studies of cultured fibroblasts showed that PTPα is indeed an important mediator of IL-1β signaling, which mediates activation of mitogen-activated protein kinases (e.g. ERK) and MMP-3 expression, which is important for connective tissue destruction in periodontitis." (PMID 23940616, 2013). "As MMP-3 is important for remodeling of inflamed gingival tissues and in periodontal tissue destruction, we used ligature-induced periodontitis and cultured fibroblasts to examine respectively, the roles of PTPα in periodontal tissue destruction and IL-1β signaling leading to MMP-3 expression." (PMID 23940616, 2013). "It has recently been shown that MMP-3 and TIMP-1 variants may significantly contribute to chronic periodontitis and disease progression." (PMID 23548063, 2013). "Therefore, unraveling the regulation of MMP-1 and MMP-3 may contribute to the development of treatments for periodontitis." (PMID 34504537, 2021). "Furthermore, the variation from the 6A allele to the 5A allele at the -1171 location of the MMP-3 gene could lead to elevated expression of the MMP, enhancing periodontal tissue destruction and the susceptibility to the development of periodontitis." (PMID 34684209, 2021). "Conversely, several other studies showed a nonsignificant trend for association of this variant with periodontitis, suggesting a likely attempt of the host environment to contain and perhaps specifically outbalance the increased MMP-3 levels to minimize tissue damage." (PMID 27194818, 2016). "A study by Ryu assessed how diabetes mellitus (DM) influences the expression of MMP-3 (stromelysin) and MMP-14 (membrane type) in the gingival tissues of patients with type 2 diabetes and healthy adults with chronic periodontitis." (PMID 40075856, 2025). "Similar alterations were observed in the longitudinal experimental periodontitis model across all age groups with elevated MMP1, MMP3, MMP9, and ALPL." (PMID 38098978, 2023). "Among these 48 crosstalk genes and the chronic periodontitis-related genes in DisGeNET, C4A, C4B, CXCL12, FCGR3A, IL1B, and MMP3 were shared and identified as the most pivotal candidate links between periodontitis and AD." (PMID 33869630, 2021). "The concentrations of MMP-3 and MMP-7 are markedly increased in the GCF of patients with periodontitis." (PMID 32650590, 2020). "There seems to be a significant increase in MMP expression and activity in chronic periodontitis, especially MMP-1, MMP-3, MMP-7, MMP-8, and MMP-9, with minor contributions from MMP-13 and MMP-14." (PMID 32650590, 2020). "BET inhibition significantly suppressed cytokine-induced mRNA expression of a broad range of inflammatory mediators involved in the pathogenesis of periodontitis, including IL8, IL1B, CCL2, CCL5, MMP3, and COX2." (PMID 31114581, 2019). "Among these promising genes, involved, or potentially involved, in periodontitis CXCL1 and MMP3 were also identified in our present study as being gene induced in young GFs in response to F. nucleatum infection." (PMID 29190775, 2017). "And based on previous studies, dramatically elevated levels of MMP-1, MMP-2, MMP-3, MMP-8, and MMP-9 have been detected in gingival crevicular fluid, peri-implant sulcular fluid, and gingival tissue of periodontitis patients." (PMID 27194818, 2016). "MMP3 and tissue inhibitor of MMPs (TIMP1) SNPs have also been considered as possible candidates in the pathogenesis of periodontitis." (PMID 29744169, 2016). "PPARγ ligands and agonists have been shown to inhibit production of MMP-3, and to prevent MMP-mediated tissue destruction in animal models of inflammation, including arthritis and periodontitis." (PMID 17319946, 2007). "The PACs also inhibited the secretion of the metalloproteinases MMP-3 and MMP-9 that actively participate in the destruction of oral tissue in periodontitis, and prevented the activation of the NF-κB signaling pathway that plays a key role in inflammatory processes." (PMID 41002732, 2025).
periodontitis (continued). "Still, our study showed that they do have an important role, as well, in discrimination between the health vs periodontitis and gingivitis vs periodontitis groups (for MMP-2) and between the health vs gingivitis groups (for MMP-3) according to the ROC analysis." (PMID 33742017, 2021). "We analyzed the MMP-3 levels in the GCF of the Stage II Grade A and Grade C periodontitis patients and of the healthy individuals, to assess whether the polymorphism had any effect." (PMID 34684209, 2021). "Although PoPEx increased the expression of both MMP-3 and TIMP-2 in LPS-stimulated P-GMSCs, the MMP-3/TIMP-2 ratio was lower than the index in only LPS-stimulated P-GMSC cultures, suggesting that PoPEx tends to restrict tissue destruction in chronic periodontitis." (PMID 37895087, 2023). "In conclusion, this meta-analysis with published data suggested that the MMP-2-753 C/T, MMP-3-1171 A5/A6, and MMP-9-1562 C/T polymorphisms were associated with periodontitis susceptibility and there is lack of association between the MMP-8-799 C/T polymorphism and periodontitis." (PMID 27095260, 2016).
prostate carcinoma (45 papers, 2006 to 2025). A carcinoma that arises from epithelial cells of the prostate gland. "Prostate cancer invasion might be suppressed by cancer-associated fibroblasts (CAFs) in which ERα was reported to modulate thrombospondin 2 (Thbs 2) and matrix metalloproteinase 3 (MMP-3)." (PMID 27186486, 2016). "Furthermore, a recent study has demonstrated that down-regulation of MMP-3 in cancer-associated fibroblasts subsequently attenuated prostate cancer cell invasion." (PMID 25596732, 2015). "To determine whether the upregulation of MMP-3 in prostate cancer cells by hydrogen peroxide is linked to miRNA-mediated posttranscriptional regulation, we first focused on miR-888, miR-6800, and miR-371, which were predicted to be mmp-3-targeting miRNAs by two algorithms (miRNA.org and TargetScan)." (PMID 28831065, 2017). "Conversely, H2O2 induces the upregulation of microRNA-128 in prostate cancer cells, which in turn reduces the expression of thrombospondin 2 (a repressor of MMP-3)." (PMID 37469162, 2024). "Frieling37 discovered that MMP3 promotes bone metastasis of prostate cancer both in vitro and in vivo and is considered a therapeutic target to inhibit the occurrence and metastasis of breast cancer." (PMID 38918587, 2024). "Reactive oxygen species–mediated switching expression of MMP-3 in stromal fibroblasts and cancer cells during prostate cancer progression." (PMID 37469162, 2024). "AQP3 overexpression increased MMP-3 secretion in prostate cancer cells and MT1-MMP, MMP-2, and MMP-9 in gastric cancer cells." (PMID 37681917, 2023). "Previous studies have demonstrated that the NFκB/MMP-3 pathway plays roles in various cell migrations, including fibroblasts, prostate cancer cells, and chondrosarcoma cells, and so on." (PMID 32711573, 2020). "In contrast to CAFs, we demonstrated for the first time that ROS increased MMP-3 expression in prostate cancer cells by upregulating miR-128, which targets the MMP-3 suppressor THBS2." (PMID 28831065, 2017). "Hydrogen peroxide reduced thrombospondin 2 (an MMP-3 suppressor) expression in prostate cancer cells by upregulating microRNA-128." (PMID 28831065, 2017). "Taken together, these results indicate that miR-128 plays a major role in hydrogen peroxide–induced MMP-3 expression in prostate cancer cells through the downregulation of THBS2." (PMID 28831065, 2017). "Although CAFs exhibited higher capacity to promote prostate cancer tumor formation, these cells expressed lower levels of MMP-3 than did normal fibroblasts." (PMID 28831065, 2017). "With this evidence, we deduced a connection between THBS2 and hydrogen peroxide/miRNA-upregulated MMP-3 in prostate cancer cells." (PMID 28831065, 2017). "By contrast, prostate cancer cells exhibited increased MMP-3 expression, which was correlated with tumor grade." (PMID 28831065, 2017). "Taken together, these results demonstrate that hydrogen peroxide is a key mediator regulating MMP-3 levels in both prostate cancer cells and environmental fibroblasts, but it acts in opposite manners in these two cellular components." (PMID 28831065, 2017). "A similar result was also observed in exogenous MMP-3 treatment group, suggesting that stromelysins (at least MMP-3) are critical for determining the invasiveness of prostate cancer." (PMID 28831065, 2017). "The MMP-3 serum level in prostate cancer patients with high-grade (Gleason score ≥ 8, n = 40) tumors was 39,883 ± 32,333 pg/ml, which was significantly higher than that in patients with benign prostatic hyperplasia (BPH) (14,494 ± 4,484 pg/ml, n = 12)." (PMID 28831065, 2017). "Herein, we demonstrated a trend of an increase in the MMP-3 level in the serum of prostate cancer patients with a pathological grade of the cancer." (PMID 28831065, 2017). "Other mechanisms contributing to the differential response to TGF-β modulating MMP-3 expression among different prostate cancer and stromal cell lines remain to be elucidated." (PMID 28831065, 2017).
prostate carcinoma (continued). "A recent study demonstrated a suppressive role of THBS2 in MMP-3 expression to modulate prostate cancer metastasis." (PMID 28831065, 2017). "Although information about MMP-3 is limited regarding prostate cancer progression, it is known that expression of MMP-3 increases in highly metastatic PC3 cells as compared to poorly metastatic LNCaP cells." (PMID 27340776, 2016). "In the presence of ATP, expressions of Snail, IL-8 and MMP-3 were significantly increased in prostate cancer cells 1E8 and 2B4, while expressions of E-cadherin and Claudin-1 were prominently reduced." (PMID 25486274, 2014). "Next, the correlation between tpx2 with mmp3, mmp9 or ets-1 in prostate carcinoma was examined." (PMID 34123781, 2021). "In vivo and in vitro studies have shown that knocking down the expression of P2 × 7 receptor significantly inhibits the ATP or BzATP-driven expression changes of EMT-related genes Snail, E-cadherin, and MMP-3, and inhibits the migration and metastasis of prostate cancer cells." (PMID 33330466, 2020). "Furthermore, hydrogen peroxide was characterized as the central modulator for altered MMP-3 expression in prostate cancer cells and CAFs, but through different regulatory mechanisms." (PMID 28831065, 2017). "However, MMP-3 was upregulated in prostate cancer cells but downregulated in CAFs isolated from prostate stroma (primary culture) or derived from bone marrow stroma (3D coculture)." (PMID 28831065, 2017). "Besides, our previous study in prostate cancer demonstrated that ATP treatment could increase the expression of MMP-3, which is extensively involved in invasion and metastasis of cancer." (PMID 25486274, 2014). "In the context of prostate cancer, H2O2 governs distinct translational regulations of matrix metalloproteinase-3 (MMP-3) in both cancer cells and CAFs." (PMID 37469162, 2024). "SPOCK1 was reported to be a regulator of the ECM and is crucial for maintaining the process of tumor ECM dynamic homeostasis through regulating the activities and expressions of MMPs such as MMP-2, MMP-3, and MMP-9 in glioma, liver cancer, and prostate cancer." (PMID 36766694, 2023). "Eotaxin can increase MMP-3 expression via the CCR3-ERK pathway, thereby promoting prostate cancer cell invasion and migration." (PMID 36661524, 2023). "In prostate cancer cells, increased H2O2 upregulated MMP-3 expression by inhibiting the MMP-3 suppressor." (PMID 34678925, 2021). "Down-regulation of HOXA1 can increase the expression of E-cadherin while reducing the expression of Snail and MMP-3, which can inhibit ERK1/2 and AKT to suppress the growth, migration, invasion and metastasis of prostate cancer." (PMID 33763449, 2020). "NADPH oxidase 1 (NOX1), which is overexpressed in colon and prostate cancers, increases levels of VEGF, VEGF receptor, and matrix metalloproteinase 3 (MMP-3)." (PMID 32645959, 2020). "In case of LNCaP, SFMBT2 interacts with YY1 and represses MMP2, MMP3, and MMP9 and inhibits invasion and migration of prostate cancer cells, and illustrating both pro and anti-role of YY1 in prostate cancer growth." (PMID 31824839, 2019). "But in a solid tumor, the IL-7/IL-7R axis promoted prostate cancer cell invasion and migration by activating the AKT/NF-κB pathway and increasing MMP-3 and MMP-7 expression." (PMID 31915416, 2019). "We found that depending on age of prostate cancer patients and Gleason score EMT genes with distinctly altered expression are: KRT18, KRT19, MUC1 and COL4A1, CTNNB1, SNAI2, ZEB1 and MMP3." (PMID 29206234, 2017). "While investigating the extracellular function of MMPs in ECM remodeling, we observed prominent nuclear immunostaining for MMP-3 and MMP-10 in the cancerous lesions of prostate cancer." (PMID 28831065, 2017).
prostate carcinoma (continued). "Consistent with the ELISA data at the protein level, real-time RT-PCR analysis showed that mmp-3 mRNA expression dose dependently decreased in HS27A stromal cells and increased in prostate cancer PC3 and DU145 cells following hydrogen peroxide treatment." (PMID 28831065, 2017). "We showed that the expression level of SFMBT2 is critical for cell migration and invasion, which are fundamental features of prostate cancer malignancy through direct or indirect regulation of MMP-2, MMP-3, MMP-9, MMP-26, N-CoR, and KAI1 gene expression." (PMID 27340776, 2016). "In conclusion, our study provides evidence that SFMBT2 regulates prostate cancer metastasis either by direct repression of YY1 target genes such as MMP-9, MMP-26, and N-CoR and by indirect regulation of MMP-2, MMP-3, and KAI1 gene expression." (PMID 27340776, 2016). "Studies have shown that knocking down the expression of P2X7R can significantly inhibit the expression of EMT/invasion-related genes Snail, Claudin-1, IL-8 and MMP-3 induced by ATP or BzATP, and inhibit the invasion, metastasis and EMT of prostate cancer cells." (PMID 40265472, 2025). "The induction of CCN2 could be a key mechanism by which MMP3 induces transformation and tumor progression, as the stromal expression of CTGF promotes angiogenesis and prostate cancer tumorigenesis." (PMID 32429403, 2020). "Treatment of CAFs but not prostate cancer cells with hydrogen peroxide directly inhibited mmp-3 promoter activity with concomitant nuclear translocation of nuclear factor-κB (NF-κB), indicating that NF-κB is the downstream pathway for the transcriptional repression of MMP-3 in CAFs." (PMID 28831065, 2017). "Collectively, these clinical observations indicate that MMP-3 alone—and not both MMP-3 and MMP-10—exhibits opposite expression patterns in stromal fibroblasts and prostate cancer cells and an overall increase in MMP-3 in patient sera." (PMID 28831065, 2017).
atherosclerosis (39 papers, 2006 to 2025). A disease characterized by the build-up of fatty material and calcium deposition in the arterial wall resulting in partial or complete occlusion of the arterial lumen. "Studies have shown that AS patients with elevated blood levels of MMP-3 have a higher likelihood of developing subclinical atherosclerosis, thereby increasing the risk of severe cardiovascular events such as myocardial infarction." (PMID 40277922, 2025). "Changes in Mmp9 and Mmp3 expression/activity are linked to cardiovascular diseases, including hypertension, lipid disorders, and atherosclerosis." (PMID 38890983, 2024). "Studies found that mice with a deficiency of MMP3 or MMP9 showed reduced macrophage infiltration in atherosclerosis in atherosclerotic plaques." (PMID 37006258, 2023). "In contrast, a common mutation in the MMP-3 promoter (which results in decreased MMP-3 expression) was associated with atherosclerosis development." (PMID 32831121, 2020). "In atherosclerosis, targeting MMP-3 may reduce plaque instability and decrease the risk of acute cardiovascular events." (PMID 40277922, 2025). "Furthermore, increased expression of MMP12 is associated with elevated expression of MMP3 and participates in the progression of atherosclerosis in transgenic rabbits." (PMID 30187887, 2018). "In this context, MMP-3 emerges as a central player, not only in the degradation of the extracellular matrix in AS but also in the pathogenesis of atherosclerosis." (PMID 40277922, 2025). "This pathway responds to inflammatory stimuli and cellular stress, with its activation contributing to MMP-3 production in both AS and atherosclerosis." (PMID 40277922, 2025). "While, the 6A-allele was associated with reduced MMP-3 expression and linked to the progression of atherosclerosis and CAD, it is suggested that the 5A allele is beneficial in atherosclerosis." (PMID 37160529, 2023). "Matrix metallopeptidase 3 (Mmp3) encodes an extracellular matrix-degrading enzyme (MMP-3) that is closely linked with tissue remodeling, wound repair, and the progression of atherosclerosis." (PMID 34307396, 2021). "Ectopic calcification conceivably leads to fewer MMP-2- and MMP-3-producing cells as in atherosclerosis, whereby calcification often corresponds to areas containing either no cells or dead cells." (PMID 33120982, 2020). "In this study we tried to find correlations of three MMP polymorphisms (–1607 1G/2G MMP1; –1612 5A/6A MMP3; –1562 C/T MMP9) with a higher risk of myocardial infarction and formation of atherosclerosis plaque." (PMID 23274712, 2013). "The lower tissue activity of MMP-3 in 6A/6A patients alters the remodeling process of ECM in the direction of facilitating the progress of atherosclerosis." (PMID 23108733, 2013). "Several genetic association studies on the role of specific MMP variants in atherosclerosis have been performed, especially with MMP1, MMP-3, and MMP-9." (PMID 23365489, 2013). "A study of a mouse model of atherosclerosis has shown that knocking out MMP3 results in increased amounts of matrix proteins in atherosclerotic lesions, a feature of more stable plaques." (PMID 20360864, 2010). "The presence of an increased risk of adenomatous polyps of the colon in coronary atherosclerosis patients suggested that the association of the MMP3 6A/6A genotype and CRC is due to its link with an increased atherosclerosis risk." (PMID 17125518, 2006). "Inhibiting PRRs or their downstream signaling pathways may thus represent a therapeutic strategy to reduce MMP-3 activation and mitigate the progression of both AS and atherosclerosis." (PMID 40277922, 2025). "Studies also found the levels of MMP1, MMP3, and MMP12 were positive associated with the degree of atherosclerosis and plaque stability, acting as valuable biomarkers for clinical diagnosis and prognosis of atherosclerosis." (PMID 37006258, 2023). "MMP3 is regarded as involved in wound repair, atherosclerosis progression and tumor initiation." (PMID 36105284, 2022).